MEX3D (mex-3 RNA binding family member D)
Description:
RNA binding protein, may be involved in post-transcriptional regulatory mechanisms.
Synonyms: KIAA2031; RKHD1; RNF193; Tino; OK/SW-cl.4; MEX-3D; MEX3
Tractability: PROTAC: ubiquitination databases record sites on it; its protein half-life has been measured.
Gene: Protein-coding gene on chromosome 19 (1,554,672 to 1,568,325, reverse strand). Ensembl gene ENSG00000181588.
Subcellular location: Cytoplasm; Nucleus
Gene Ontology:
Molecular function: mRNA 3'-UTR AU-rich region binding; RNA binding; nucleic acid binding
Biological process: mRNA destabilization; mRNA localization resulting in post-transcriptional regulation of gene expression
Cellular component: nucleus; perinuclear region of cytoplasm; cytoplasm
Genetic constraint (gnomAD): Loss-of-function variants: 4 observed, 4.28 expected, observed/expected ratio (o/e) 0.93, 90% interval 0.45 to 1.8. That is too few expected variants to judge how well the gene tolerates losing a copy. Missense variants: 885 observed, 691.06 expected, observed/expected ratio (o/e) 1.28, 90% interval 1.21 to 1.35. Synonymous variants: 551 observed, 358.43 expected, observed/expected ratio (o/e) 1.54, 90% interval 1.43 to 1.65.
Homologues: Orthologues: macaque MEX3D (97% identical), chimpanzee MEX3D (90% identical), pig MEX3D (86% identical), dog MEX3D (80% identical), rat Mex3d (79% identical), mouse Mex3d (78% identical), tropical clawed frog mex3d (50% identical). Paralogues in human: MEX3B (47% identical), MEX3C (40% identical), MEX3A (37% identical).
Diseases named in the same sentence as MEX3D in open-access papers:
MEX3D is named in the same sentence as 20 diseases in open-access papers, as found by Europe PMC text mining. Sharing a sentence is not in itself a finding about the gene and the disease. The quoted sentences say what the papers report.
prostate carcinoma (4 papers, 2014 to 2022). A carcinoma that arises from epithelial cells of the prostate gland. "Previous studies have shown that MEX3D is an oncogenic driver in prostate cancer." (PMID 35513372, 2022). "It was reported that MEX3D could promote proliferation of cervical carcinoma and transformation of prostatic epithelium in prostate cancer." (PMID 36398070, 2022). "Using this approach, the RIS were identified near a known prostate cancer gene PTRF as well as other genes that were not previously implicated in prostate cancer including ATPAF1, GCOM1, MEX3D, and TRPM4." (PMID 27792127, 2016).
cervical carcinoma (2 papers, 2022). A carcinoma arising from either the exocervical squamous epithelium or the endocervical glandular epithelium. "In this present study, the functional roles and the regulatory mechanisms underlying MEX3D were examined in cervical cancer." (PMID 35513372, 2022). "In cervical cancer, the underlying molecular mechanism of the MEX3D cancer-promoting effects was investigated." (PMID 35513372, 2022). "TSC22D1 was found to be a critical inhibitory factor in the carcinogenesis of cervical cell, and TSC22D1 is essential for reducing the tumorigenic potential of cervical cancer cells induced by MEX3D." (PMID 35513372, 2022). "Two sequences of MEX3D-specific small interfering RNA (siRNA) were utilized to eliminate MEX3D expression in CaSki and SiHa cervical cancer cells." (PMID 35513372, 2022). "Knocking down MEX3D expression decreased cervical cancer growth and promoted apoptosis in both CaSki and SiHa cells." (PMID 35513372, 2022). "When MEX3D expression was knocked down in cervical cancer cells, cell proliferation was decreased, colony formation was inhibited, and apoptosis was promoted." (PMID 35513372, 2022). "The current study presented a theoretical basis for using this target in the management of patients with cervical cancer and identified a new post-transcriptional mechanism involving MEX3D-mediated TSC22D1 transcript destabilization." (PMID 35513372, 2022). "In our previous RNA sequencing (RNA-seq) results, in cervical cancer tissues, MEX3D mRNA expression was elevated compared to the corresponding expression noted in normal cervical tissues." (PMID 35513372, 2022). "The function of the RBP MEX3D and its mechanism of action in cervical cancer were highlighted in this work." (PMID 35513372, 2022). "Initially, the identification of the endogenous RNA targets of MEX3D was performed in cervical cancer cells by high-throughput RNA immunoprecipitation (RIP) sequencing (analyzed by RiboBio, Guangzhou, China)." (PMID 35513372, 2022). "MEX3D mRNA was noticed to be substantially elevated in cervical cancer tissues than the corresponding expression noticed in normal cervical tissues in our prior RNA-seq data." (PMID 35513372, 2022). "When compared to normal cervical tissues, MEX3D expression was observed to be higher in cervical cancer tissues." (PMID 35513372, 2022). "MEX3D expression was increased in human papillomavirus (HPV) 16 positive cervical cancer tissues and positively regulated by HPV16 E7." (PMID 35513372, 2022). "A rescue experiment was carried out to see if TSC22D1 was involved in the consequences of MEX3D-mediated carcinogenesis in cervical cancer cells." (PMID 35513372, 2022). "The RNA-binding protein MEX3D role as a tumor promoter in cervical cancer was assessed in this study." (PMID 35513372, 2022). "In cervical cancer tissue specimens, MEX3D mRNA expression levels were significantly elevated than in normal cervix specimens." (PMID 35513372, 2022). "Considering that uncontrolled cell proliferation is a hallmark of cancer, this study evaluated whether inhibiting MEX3D suppressed the proliferation of cervical cancer cells." (PMID 35513372, 2022). "According to the findings of this study, MEX3D may be a potential therapeutic target for treating cervical cancer patients." (PMID 35513372, 2022). "In cervical cancer, the role and expression of MEX3D, however, are poorly understood." (PMID 35513372, 2022). "Similarly, expression level of MEX3D protein was higher in HPV16-positive cervical cancer than in HPV16-positive HSIL tissues." (PMID 35513372, 2022). "We further investigated whether the increased expression of MEX3D in cervical cancer was regulated by E6 or E7." (PMID 35513372, 2022). "Taken together, these data reinforce the hypothesis suggesting that MEX3D serves as a tumor promoter in cervical cancer progression and facilitates the malignant phenotype of cervical cancer." (PMID 35513372, 2022).
cervical carcinoma (continued). "In addition, MEX3D overexpression induced cervical cancer cell proliferation and attenuated apoptosis." (PMID 35513372, 2022). "MEX3D expression was higher in human cervical cancer cells, suggesting that it may be a strong predictor for cervical cancer tumorigenesis in this study." (PMID 35513372, 2022). "In this study, the RBP MEX3D was assessed with regard to its oncogenic role in cervical cancer." (PMID 35513372, 2022). "Therefore, the data indicated that high MEX3D expression acted as a tumor promoter in cervical cancer progression." (PMID 35513372, 2022). "The data indicated that MEX3D was associated with TSC22 domain family protein 1 (TSC22D1) RNA levels and that TSC22D1 knockdown could reverse MEX3D knockdown-induced tumorigenesis in cervical cancer cells." (PMID 35513372, 2022). "In addition, this revealed that MEX3D expression knockdown might inhibit cervical cancer cell proliferation." (PMID 35513372, 2022). "The findings suggested that MEX3D, as an oncogene, may have a role in cervical cancer." (PMID 35513372, 2022). "Furthermore, MEX3D protein expression was considerably greater in cervical cancer tissues." (PMID 35513372, 2022). "Therefore, the present study demonstrated that in cervical cancer, MEX3D could be utilized as therapeutic target and potential diagnostic." (PMID 35513372, 2022). "Therefore, they were identified as possible MEX3D targets in cervical cancer." (PMID 35513372, 2022). "It is interesting to note that MEX3D protein overexpression was noted in HSIL and cervical cancer samples compared to LSIL or normal tissues." (PMID 35513372, 2022). "The findings revealed that MEX3D is upregulated by HPV16 E7 and has a crucial oncogenic in cervical cancer development via sponging TSC22D1 for destabilizing its mRNA levels." (PMID 35513372, 2022). "Given that TSC22D1 is a key MEX3D downstream effector, the current study characterized the TSC22D1 functional role in tumorigenesis of cervical cancer." (PMID 35513372, 2022). "Following that, the MEX3D protein expression level was assessed in 465 cervical tissues, comprising 30 normal cervix tissues, 147 low-grade squamous intraepithelial lesions (LSIL), 129 high-grade squamous intraepithelial lesions (HSIL), and 159 cervical cancer tissues." (PMID 35513372, 2022).
acute myeloid leukemia (1 paper, 2014). Acute myeloid leukemia (AML) is a group of neoplasms arising from precursor cells committed to the myeloid cell-line differentiation. "MEX3D was previously associated with chemotherapy-induced oral mucositis in acute myeloid leukemia patients." (PMID 24885513, 2014).
large cell lung cancer (1 paper, 2023). "MEX3A was expressed in LUAD, LUSC and large cell lung cancer (LCLC); MEX3B was detected in LCLC; and MEX3D was expressed in LUAD." (PMID 36507941, 2023).
ovarian carcinoma (1 paper, 2018). A malignant neoplasm originating from the surface ovarian epithelium. "We found that only SORBS2 and MEX3D gene knock down significantly increased the metastatic colonization capacity of ovarian cancer." (PMID 29548303, 2018). "Among all these RBP genes, only four showed deletion in more than 5% of TCGA ovarian cancer samples, including transcription factor BTF3, sorbin and SH3 domain-containing protein 2 (SORBS2), cold-inducible RNA-binding protein (CIRBP), and RNA-binding protein MEX3D (MEX3D)." (PMID 29548303, 2018).
pterygium (1 paper, 2022). A wedge-shaped fibrovascular lesion arising from the bulbar conjunctiva and extending to the cornea. "We speculated that these highly expressed circRNAs may increase the expression of FN1, SDC2, and MEX3D by sponging miR-200b-3p and further promote pterygium formation and growth." (PMID 36398070, 2022).
cancer (13 papers, 2012 to 2026). A tumor composed of atypical neoplastic, often pleomorphic cells that invade other tissues. "The data indicated that the MEX3D/TSC22D1 complex regulated cancer-associated functions as a consequence of HPV16 E7 overexpression." (PMID 35513372, 2022). "Moreover, MEX3D is frequently deleted in various human cancers, participates in modulating the effectiveness of chemotherapy in AML (acute myeloid leukaemia), and is overexpressed in androgen-independent prostate cancer." (PMID 36507941, 2023). "Even so, the MEX3D gene function in cancer is poorly characterized." (PMID 35513372, 2022). "To explore the role of the MEX3 family in cancers, we used TCGA for pan-cancer analysis of the expression of MEX3A, MEX3B, MEX3C and MEX3D." (PMID 38914858, 2024). "Gaviscon formulations also revealed the downregulation of various genes such as COL6A2, DOHH, MEX3D, SBNO2, which have roles in cancer or chronic disease progression." (PMID 39409043, 2024). "One of these proteins, Mex-3 RNA-binding family member D (MEX3D), has been recently found to exhibit oncogenic properties in a variety of cancer types." (PMID 35513372, 2022).
tumor (10 papers, 2014 to 2025). "Then HPV16 E7 siRNA sequences underwent incubation in CaSki and SiHa cells to examine if MEX3D is implicated in the tumor-promoting properties of HPV16 E7." (PMID 35513372, 2022). "MEX3D, a Mex-3 RNA-binding family member, plays a role in the pathological and physiological processes of tumor differentiation, proliferation, autophagy, apoptosis, and inflammation." (PMID 39199384, 2024). "Next, epigenetic analysis via LC-MS/MS reveals higher m6A-abundance in ALKBH5-deficient as compared to FTO-deficient B16 tumours, which meaningfully suppresses the expression of m6A-mediated ‘Mct4/Slc16a3’ in ALKBH5 alone and ‘Mex3d’ in ALKBH5 and FTO both." (PMID 34571899, 2021). "Finally, we found that MEX3D was statistically related to tumour purity and positively related to CD4+ T cells, macrophages and neutrophils." (PMID 36507941, 2023). "Promising candidates identified from the androgen-independent in vivo tumor were GCOM1 (GRINL1A complex locus 1), MEX3D (mex-3 RNA binding family member D), and PTRF (polymerase I and transcript release factor)." (PMID 24885513, 2014). "MEX3D played a vital role by reducing TSC22D1 mRNA stability in apoptosis and tumor growth." (PMID 35513372, 2022).
MEX3D also shares sentences with these, for which no sentence is quoted: glioma (2 papers); astrocytoma (1); gastric cancer (1); glioblastoma (1); lung carcinoma (1); multiple myeloma (1); nasal polyps (1); non-small cell lung carcinoma (1); oral mucositis (1); squamous intraepithelial lesions (1); sterility (1); triple-negative breast carcinoma (1).